ABCB1 (ATP binding cassette subfamily B member 1)
Diseases named in the same sentence as ABCB1 in open-access papers (continued):
Sharing a sentence is not in itself a finding about the gene and the disease.
osteosarcoma (106 papers, 1998 to 2025). A usually aggressive malignant bone-forming mesenchymal neoplasm, predominantly affecting adolescents and young adults. "In a three-dimensional osteosarcoma model, the increased expression of several drug-resistance-related genes (Bcl2, Abcb1, Abcg2, Nanog, Sox2) was closely associated with heightened glutamine metabolism." (PMID 41300631, 2025). "On the other hand, elevated levels of ABCB1 have also been shown to be associated with paclitaxel resistance in human osteosarcoma (OS) cell lines, which developed cross-resistance with other ABCB1 substrates, such as doxorubicin, docetaxel, and vincristine." (PMID 38026933, 2023). "The clinical response to conventional chemotherapy in osteosarcoma is limited due to drug resistance, caused by the overexpression of ABCB1." (PMID 27566582, 2017). "We further demonstrated that expression of P-gp can be efficiently blocked by the CRISPR-Cas9 system and inhibition of ABCB1 was associated with reversing drug resistance in osteosarcoma MDR cell lines (KHOSR2 and U-2OSR2) to doxorubicin." (PMID 27835872, 2016). "Inhibition of ABCB1 was associated with reversing drug resistance in osteosarcoma MDR cell lines (KHOSR2 and U-2OSR2) to doxorubicin." (PMID 27835872, 2016). "The results showed that individuals with ABCB1 TT genotype and T allele were associated with high risk of death from osteosarcoma when compared with wide-type genotype, with HRs(95%CI) of 2.58(1.03-7.28) and 1.65(1.03-2.72), respectively." (PMID 25097538, 2014). "Cox regression analysis showed that individuals with ABCB1 TT genotype and T allele were associated with high risk of death from osteosarcoma when compared with wide-type genotype." (PMID 25097538, 2014). "Notably, exosomes derived from chemoresistant osteosarcoma cells have been shown to carry functional P-glycoprotein (P-gp/ABCB1), a membrane-associated ATP-binding cassette (ABC) transporter." (PMID 41383602, 2025). "Thus, the amplification of ABCB1 expression is a common pathway to DXR resistance in cells from osteosarcomas caused by FOXC2-AS1 and FOXC2." (PMID 39015175, 2024). "Several studies have proposed a mechanism of drug resistance using HDACi agents for osteosarcoma in which the multidrug resistance protein 1 (MDR1) encoded by the ABCB1 gene is upregulated in doxorubicin-resistant OS cells, which are also resistant to HDACi agents." (PMID 34439353, 2021). "ABCB1 C3435T polymorphism may be used as a genetic predicator of clinical outcome in osteosarcoma patients treated with chemotherapy." (PMID 25097538, 2014). "ABCB1 3435TT genotype and T allele may be associated with the clinical outcome of osteosarcoma patients in a Chinese population." (PMID 25097538, 2014). "The other SNPs we found associated with osteosarcoma survival are located in the ABCB1 gene." (PMID 22016816, 2011). "Notably, the lncRNA ODRUL may diminish DXR susceptibility in osteosarcoma cells owing to its ability to amplify ABCB1 expression." (PMID 39015175, 2024). "In osteosarcoma, a key mechanism by which CAFs mediate therapeutic resistance is through induction of ABCB1/P−glycoprotein in tumor cells, leading to active efflux of chemotherapy agents." (PMID 40959080, 2025). "The high expression level of ODRUL is related to the induction of ABCB1 gene and results in the emergence of doxorubicin resistance in osteosarcoma." (PMID 40352931, 2025). "Knockdown of the expression level of ODRUL leads to a decrease in the expression level of ABCB1 gene and improves the responsiveness of osteosarcoma toward doxorubicin." (PMID 40352931, 2025). "For example, in osteosarcoma tissues and DOX-resistant osteosarcoma cells, miR-198 targets and upregulates ABCB1 expression, increasing the sensitivity of osteosarcoma cells to doxorubicin and thereby enhancing drug efficacy." (PMID 39857292, 2025).
osteosarcoma (continued). "ABCB1 plays a crucial role in OS chemoresistance to doxorubicin by actively transporting the drug out of osteosarcoma cells, thus reducing its cytotoxic effects." (PMID 40283955, 2025). "On the other hand, the ABC transporters (including the ABCC3 and ABCB1 gene products) are transmembrane ATP-dependent efflux pumps that block chemotherapy drugs from entering osteosarcoma tumour cells, leading to poor outcomes and systemic toxicity." (PMID 39335211, 2024). "In our study, the ABCC3 and ABCB1 genes in the osteosarcoma tissues were significantly downregulated compared to the healthy donors." (PMID 39335211, 2024). "Fendrr enhances doxorubicin resistance in doxorubicin-resistant and-sensitive human osteosarcoma cells by negatively regulating the post-transcriptional expression of the multidrug resistance-related proteins ABCB1 and ABCC1." (PMID 36719027, 2023). "A study of drug-resistant osteosarcoma cells showed that targeting CD44 using CRISPR/Cas9 technology reduced ABCB1 expression and significantly increased doxorubicin sensitivity." (PMID 35715750, 2022). "More interestingly, miR-34b was reported to directly target ABCB1 mRNAs and increase the sensitivity of human osteosarcoma cells to multiple chemotherapeutic agents." (PMID 34055636, 2021). "In osteosarcoma, circPVT1 has been found to confer multidrug resistance by upregulating ABCB1 expression." (PMID 33793089, 2021). "Enhancing the anti-tumor activity of endogenous Vγ9Vδ2 T-cells against ABCB1-positive osteosarcoma, where doxorubicin fails, can be a step forward in the immune-therapy-based treatments for aggressive osteosarcomas." (PMID 32155954, 2020). "The ATP Binding Cassette transporter B1 (ABCB1) induces chemoresistance in osteosarcoma, because it effluxes doxorubicin, reducing the intracellular accumulation, toxicity, and immunogenic cell death induced by the drug." (PMID 32155954, 2020). "The active efflux of doxorubicin by ABCB1 is the main mechanism of resistance to doxorubicin in osteosarcoma, limiting the drug’s intracellular accumulation and cytotoxicity." (PMID 32155954, 2020). "Unexpectedly, in osteosarcoma cells with acquired resistance to doxorubicin and high levels of ABCB1, the amount of ABCA1 was reduced." (PMID 32155954, 2020). "We would like to investigate if they can represent an endogenous immune-weapon against ABCB1-expressing osteosarcoma cells that escape the classical CD8+T-lymphocyte-mediated immune-killing." (PMID 32155954, 2020). "To address this question, we examined the expression levels and the molecular circuitries regulating ABCA1 in human osteosarcoma cells with different levels of ABCB1." (PMID 32155954, 2020). "It has been reported that miR-9 can bind to the 3'-UTR of ABCB1 and trigger its decay in the chemoresistant osteosarcoma cells." (PMID 31938057, 2020). "This phenotype was observed also in 3D cultures of osteosarcoma derived from doxorubicin-sensitive cells, which up-regulated ABCB1 and displayed resistance to doxorubicin, as it occurs in colon and breast cancer cells." (PMID 32155954, 2020). "Since cell proliferation is closely associated with drug resistance, lncRNA LUCAT1 promotes methotrexate resistance in osteosarcoma by regulating the miR-200c/ABCB1 axis." (PMID 31777598, 2019). "LncRNA FENDRR was found to sensitize doxorubicin-resistance of osteosarcoma cells through down-regulating ABCB1 and ABCC1." (PMID 30153287, 2018). "At the same time, FOXC2 contributes to the resistance of osteosarcoma by inducing expression of ABCB1." (PMID 29657304, 2018). "We found that lncRNA FENDRR was the most down-regulated lncRNA in the doxorubicin-resistant osteosarcoma cells and possibly acted as a drug-resistance suppressing molecule through inhibiting ABCB1 and ABCC1 expression." (PMID 29069754, 2017). "A study of an ABCB1/ABCC1 inhibitor found that in osteosarcoma cell lines, the inhibitor was able to revert the ABCB1/ABCC1-mediated resistance against doxorubicin." (PMID 27566582, 2017).
osteosarcoma (continued). "Then we adopted the CRISPR-Cas9, a robust and highly efficient novel genome editing tool, to determine its effect on reversing drug resistance by targeting endogenous ABCB1 gene at the DNA level in osteosarcoma MDR cell lines." (PMID 27835872, 2016). "In both osteosarcoma cell lines investigated, promoter methylation levels of ABCB1 and ABCG2 were in the range from 10 to 17%." (PMID 27689338, 2016). "ABCB1 efflux pump expression has been suggested as a major regulator of osteosarcoma chemotherapy response." (PMID 26526352, 2015). "In this study, we planned to investigate the role of three genetic polymorphisms (ABCB1 C3435T, ABCG2 c421A, and ABCC3 C-211T) in response to chemotherapy and overall survival of osteosarcoma patients." (PMID 25097538, 2014). "Cox regression analysis of association between ABCB1 C3435T, ABCG2 C421A and ABCC3 C-211T polymorphisms and the survival of osteosarcoma were showed in Table-IV." (PMID 25097538, 2014). "CHA59, Saos-2, and HuO9 were immunoprobed for the expression of cell surface markers (CD133, CD24, CD166, CD326, CD44, ABCB1, ABCC1, ABCG2) previously reported to be associated with TSCs and/or osteosarcoma." (PMID 22870217, 2012). "Furthermore, targeted disruption of ABCB1 using CRISPR/Cas9 has been shown to restore doxorubicin sensitivity in resistant osteosarcoma cell lines (e.g., KHOSR2, U-2OSR2), further confirming the role of CAFs-induced signaling in drug resistance." (PMID 40959080, 2025). "ATP-binding cassette subfamily B member 1 (ABCB1) effluxes doxorubicin, reducing its intracellular accumulation and diminishing both its toxicity and the immunogenic cell death it induces, thereby contributing to chemoresistance in osteosarcoma." (PMID 40370434, 2025). "Since ABCB1 and ABCC3 proteins are relevant for preserving liver integrity at high doses of MTX, these variants are promising biomarkers for MTX-induced hepatotoxicity in localized osteosarcoma patients." (PMID 39771563, 2024). "For example, overexpression of circPVT1 could enhance doxorubicin and cisplatin resistance of osteosarcoma cells by regulating ABCB1." (PMID 35230201, 2022). "Moreover, the ABCB1: ABCA1 ratio was reportedly upregulated in osteosarcoma cells and positively correlated with a higher probability of relapse." (PMID 35837087, 2022). "Four members of ABC family have been shown to contribute to multidrug resistance in osteosarcoma, including MDR1 (also called P-glycoprotein, P-gp or ABCB1), multidrug resistance-associated protein 1 and 2 (MRP1/ABCC1 and MRP2/ABCC2), and breast cancer resistance protein (BCRP/ABCG2)." (PMID 35955749, 2022). "The results of a meta-analysis also showed that targeting the ABCB1 gene using CRISPR/Cas9 technology could attenuate doxorubicin resistance in drug-resistant osteosarcoma cells." (PMID 35715750, 2022). "Moreover, about 40%–45% of patients with high-grade osteosarcoma are either only partially responsive or completely unresponsive to doxorubicin (Dox), due to the increased drug efflux by the transporter protein ABCB1." (PMID 32397561, 2020). "In this work, we analyzed how ABCA1 and ABCB1 are regulated in osteosarcoma, and if increasing the ABCA1-dependent activation of Vγ9Vδ2 T-cells could be an effective strategy against ABCB1-expressing osteosarcoma." (PMID 32155954, 2020). "Recruiting this population may represent an alternative strategy to rescue doxorubicin efficacy in ABCB1-expressing osteosarcoma." (PMID 32155954, 2020). "In osteosarcoma, the presence of ABCB1 is predictive of poor response to chemotherapy." (PMID 32155954, 2020). "Previous studies prove that ABCB1 is a classical ATP-dependent drug efflux pump and plays key roles in the drug resistance of various tumors, such as gastric cancer, urothelial cancer, lobular breast cancer, osteosarcoma and so on." (PMID 30760665, 2019). "circPVT1 knockdown sensitizes osteosarcoma cells to cisplatin by decreasing ABCB1 expression." (PMID 31372241, 2019).
osteosarcoma (continued). "In the present study, we observed whether there were more valuable genes like ABCB1 which could help improve and modify chemotherapy regimens in osteosarcoma." (PMID 29850522, 2018). "Additionally, the drug-resistance related protein ATP binding cassette subfamiliy B member 1 (ABCB1) is likewise overexpressed in MTX-resistant osteosarcoma cell-lines MG63/MTX and HOS/MTX." (PMID 29657304, 2018). "Another study has revealed that downregulated circPVT1, which is overexpressed in osteosarcoma tissues and chemoradiation-resistant cells, can weaken expression of the classical chemoradiation resistance gene ABCB1 to reduce the resistance to cisplatin and doxorubicin in osteosarcoma cells." (PMID 30126353, 2018). "Therefore, FOXC2-AS1 and FOXC2 seem to contribute to DXR-resistance in osteosarcoma cells by both enhancing ABCB1-expression." (PMID 29657304, 2018). "Mechanistically, ODRUL may increase doxorubicin resistance by inducing the expression of a classic multidrug resistance-related ABCB1 gene in human osteosarcoma cell lines." (PMID 28353666, 2017). "In this study, we adopted the CRISPR-Cas9 system to knockout ABCB1 in osteosarcoma MDR cell lines." (PMID 27835872, 2016). "However, ABCB1 gene expression detected by real-time PCR was comparably low in all osteosarcoma cell lines making this assumption unlikely." (PMID 26526352, 2015). "Additionally, targeting the Ras/Akt/mTOR and Ras/ERK1/2/HIF-1α pathways with self-assembling nanoparticles encapsulating zoledronic acid (NZ) can simultaneously upregulate ABCA1 and downregulate ABCB1, thereby restoring drug sensitivity in doxorubicin-resistant osteosarcoma." (PMID 40283955, 2025). "A.770041 reverses ABCB1/Pgp‐mediated chemotherapy drug resistance in osteosarcoma, and a combination of A.770041 with regular chemotherapy drugs may be clinically effective in multi‐drug resistant osteosarcoma." (PMID 38090653, 2022). "In addition, we found that FENDRR was mainly located in the cytoplasm and could regulate the drug resistance of osteosarcoma cells by negatively affecting posttranscriptional expression of ABCB1 and ABCC1." (PMID 29069754, 2017). "ABCB1 knockout could restore the sensitivity of osteosarcoma MDR cell lines to doxorubicin." (PMID 27835872, 2016). "Therefore, we investigated that polymorphisms in ABCB1, ABCG2 and ABCC3 could be a predictor for treatment response for osteosarcoma patients." (PMID 25097538, 2014). "ABCB1 expression is also promoted by FOXC2, which adds to the drug resistance seen in osteosarcomas." (PMID 39015175, 2024). "The expression of ABCB1 and ABCC3 in osteosarcoma metastatic tumour biopsies confers impoverished event-free and overall survival outcomes." (PMID 39335211, 2024). "Given the well-known roles of ABCB1 and MRP-1 in multidrug resistance, their expression levels were detected in osteosarcoma by a western blot assay." (PMID 33981772, 2021). "Meanwhile, our data suggested that the protein levels of ABCB1 and MRP-1 were increased in DXR-resistant osteosarcoma cells (KHOS/DXR and U2OS/DXR) in comparison with parental osteosarcoma cells (KHOS and U2OS)." (PMID 33981772, 2021). "In this study, the high expression of ABCB1 and MRP-1 was viewed in DXR-resistant osteosarcoma tissues and cell lines, confirming the drug resistance of osteosarcoma tissues and cells." (PMID 33981772, 2021). "For example, circPVT1 was up-regulated in osteosarcoma, and enhanced the resistance of osteosarcoma cells to DDP via up-regulating the expression of ABCB1." (PMID 32581651, 2020).
osteosarcoma (continued). "In conclusion, we demonstrated that ABCB1 and ABCA1 are inversely expressed in doxorubicin-sensitive and doxorubicin-resistant osteosarcoma cells." (PMID 32155954, 2020). "In humanized mice, NZ reduced the growth of chemo-immune-resistant osteosarcomas, increased intratumor necro-apoptosis, and ABCA1/ABCB1 ratio and Vγ9Vδ2 T-cell infiltration." (PMID 32155954, 2020). "Overall, these data demonstrate that ABCB1 is high and ABCA1 is low in doxorubicin-resistant osteosarcoma cells." (PMID 32155954, 2020). "The main mechanism of resistance to Dox in osteosarcoma is the presence of the ATP binding cassette transporter B1 (ABCB1), also known as P-glycoprotein (Pgp), which effluxes Dox outside the cells limiting its intracellular accumulation and toxicity." (PMID 32599901, 2020). "In another study, lncRNA ENST00000563280 and NR-036444 were found to interact with critical cancer genes such as ABCB1, HIF1A, and FOXC2 to modulate doxorubicin-resistance in osteosarcoma patients." (PMID 28122578, 2017). "Then, we adopted the CRISPR-Cas9 system to specifically inhibit ABCB1 at the DNA level in osteosarcoma MDR cells, and further determined the effects of ABCB1 knockout on reversing drug resistance in osteosarcoma MDR cells." (PMID 27835872, 2016). "Strategies for reversing and preventing MDR by targeting ABCB1 have been studied extensively in different MDR model systems, including in osteosarcoma, but have shown limited clinical potential." (PMID 27835872, 2016). "These engage with genes including ABCB1, HIF1A and FOXC2, which may contribute to elevated levels of osteosarcoma resistance to DXR." (PMID 39015175, 2024). "However, decreasing the expression levels of MDR1/ABCB1 and MRP1/ABCC1 in U-2OS/Dox increased the chemosensitivity of drug-resistant osteosarcoma cells to doxorubicin." (PMID 38420199, 2024). "Additionally, an increased expression of drug efflux transporters ABCB1 and ABCG2 was observed in osteosarcoma cancer stem cells." (PMID 36769824, 2023). "More importantly, our results verified that the knockdown of circPVT1 could block ABCB1 and MRP-1 levels in DXR-resistant osteosarcoma cells, implying that circPVT1 silencing might mitigate the drug resistance of osteosarcoma cells." (PMID 33981772, 2021). "ABCB1 P-glycoprotein positivity was also evaluated on a metastatic specimen resected previously to treatment as a negative prognostic factor in osteosarcoma." (PMID 32398946, 2020). "We found that ABCB1 and ABCA1 are inversely expressed in osteosarcoma cells." (PMID 32155954, 2020). "In a limited series of high-grade osteosarcomas, a non-significant trend of the high ABCB1 mRNA levels or the low ABCA1 mRNA levels at diagnosis toward a worse relapse-free survival." (PMID 32155954, 2020). "Together, our study demonstrated that lncRNA FENDRR may act as an inhibitory molecule of doxorubicin-resistance through down-regulating the expression of ABCB1 and ABCC1 genes in osteosarcoma cells." (PMID 29069754, 2017). "Knockout of ABCB1 by CRISPR-Cas9 restored the sensitivity of osteosarcoma MDR cell lines to doxorubicin, but not to cisplatin." (PMID 27835872, 2016). "Cell-based screening of a preselected kinase-based small molecule compound library identified A-770041 as one of the most effective drug resistance reversing agents in two osteosarcoma MDR cell line models, U-2OSMR and KHOSR2, having defined overexpression of the major MDR transporters, ABCB1/Pgp." (PMID 25236161, 2014). "In 3D cultures of ABCB1-high/ABCA1-low chemo-immune-resistant cells, expression of the doxorubicin effluxer ABCB1 was upregulated by the Ras/ERK1/2/HIF-1α signaling axis, which suggests the existence of pathway crosstalk to reinforce an already chemoresistant phenotype in osteosarcoma cells." (PMID 36232719, 2022).